APOE (apolipoprotein E)
Diseases named in the same sentence as APOE in open-access papers (continued):
Sharing a sentence is not in itself a finding about the gene and the disease.
Cognitive impairment (continued). "It is still unclear whether the majority of the detected associations between the three neighboring genes and cognitive impairment are independent of APOE genetic variation or driven at least partially by LD with APOE." (PMID 29739406, 2018). "Therefore, further studies are needed to clarify the role of APOE in PD cognitive impairment." (PMID 29692703, 2018). "Notably, the mother of a patient who carried the mutation together with an APOE 4–4 genotype had no cognitive impairment until the age of 85, when she presented recurrent lobar hematoma." (PMID 28350801, 2017). "Together, the results suggested that in 7,8-DHF-treated group, significant differences were found in the expression of p-TrkB, p-AKT, and p-GSK3β, which suggested that 7,8-DHF might play a role in ameliorate cognitive impairment in ApoE-KO mice by regulating AKT/GSK3β pathway." (PMID 27965573, 2016). "But whether it could ameliorate cognitive deficits in ApoE-KO mice was still unknown." (PMID 27965573, 2016). "However, there is evidence that APOE-related cognitive deficits may be exacerbated in combination with other vulnerability factors, such as head injury, vascular disease, and accumulation of β-amyloid, thereby exerting large effects for some individuals." (PMID 26252210, 2015). "Additionally, subjects without APOE-4 alleles who reported use of CCBs showed significantly slower progression to severe global cognitive impairment (~4 years)." (PMID 26221415, 2015). "Given that cognitive deficits in e4+ have been detected as early as 60 years, studies examining APOE effects on cognitive performance at mid-age should focus on a narrower age range that might better isolate the transition into poorer age-related cognitive change in e4+." (PMID 24582638, 2014). "Further support for a critical role of apoE-mediated removal of beta-amyloid are recent studies demonstrating the administration of anti-cancer drug, bexarotene in an animal model of AD, enhanced clearance of beta-amyloid and reversed cognitive impairments in an apoE-dependent manner." (PMID 23867607, 2013). "Sex- and apoE genotype–related GABAergic interneuron alterations in the auditory cortex were examined as an extra-hippocampal control, as this area has no known role in cognitive deficits associated with AD." (PMID 23300939, 2012). "The APOE ε4 allele is a well-established genetic risk factor for Alzheimer's disease (AD) and influences episodic memory negatively in aging individuals, even in the absence of AD or mild cognitive impairment." (PMID 22506016, 2012). "Therefore, APOE genotype may be related to cognitive function many years before cognitive impairment becomes clinically apparent." (PMID 22110642, 2011). "Moreover, research has shown that the apolipoprotein E (APOE) ε2 allele exhibits a protective effect against cognitive impairment exclusively in the Han, but not in the Hui—the largest minority population in China—suggesting distinct nationality-specific risks for cognitive impairment." (PMID 40808837, 2025). "Moreover, its significant correlations with oxidative stress indicators (GSH, MDA) and cognitive function (LOTCA score), suggesting that ApoE may not only be involved in the metabolic response after TBI, but also be closely associated with oxidative imbalance and cognitive impairment." (PMID 41394006, 2025). "The results therefore underscore that APOE ε4 influences NPS and cognitive impairment through partially distinct mechanisms." (PMID 39974048, 2025). "Among APOE ε4 non-carriers, moderate (OR = 0.66, 95%CI = 0.48 ~ 0.92, P-value = 1.43 × 10− 2) and high PA levels (OR = 0.59, 95%CI = 0.46 ~ 0.75, P-value = 2.68 × 10− 5) were significantly associated with lower risk of cognitive impairment compared to low PA levels." (PMID 39789564, 2025).
Cognitive impairment (continued). "During the prodromal or mild cognitive impairment (MCI) phase, tau pathology emerges, and subtle cognitive deficits appear, with ongoing ApoE- and lipid-mediated effects on protein clearance, membrane composition, and synaptic function." (PMID 41210483, 2025). "Donanemab, the newest, received FDA approval July 2024 for early AD (including mild cognitive impairment with supportive imaging evidence) and received UK MHRA approval in October 2024 with similar exclusion criteria proposed around the APOE carrier status." (PMID 40149482, 2025). "The KSS-2 will determine how the genotypes (e.g., ALDH2, ADH1B, and APOE), SVD burden, and/or lifestyle factors interact with cognitive impairment, cerebral cardiovascular disease, and death." (PMID 40603063, 2025). "As predicted, significant differences were observed across neuropsychological test scores (e.g., MoCA‐B and ACE‐III), APOE ε4 positivity rates and AD PET imaging findings (Aβ and tau deposition) as cognitive impairment progressed (all p < 0.001)." (PMID 40717521, 2025). "In addition to documented pathogenic mutations in PD genes, common genetic variants in at least three genes, apolipoprotein E (APOE), microtubule-associated protein tau (MAPT), and α-synuclein (SNCA), may play a role in the eventual susceptibility to cognitive impairment in PD patients." (PMID 40722695, 2025). "Our sample comprised a higher percentage of APOE ɛ4 carriers within Hispanic participants of varying ancestries than other studies, which may reflect differences in recruitment sources and a bias towards presence of cognitive impairment in tertiary clinics typical of ADRC populations." (PMID 37671801, 2024). "Another study based on the same dataset demonstrated that the relationship between psychosis and incident cognitive impairment, as assessed by the MBI-C, was modified by the APOE genotype." (PMID 38473892, 2024). "Finally, the apolipoprotein E genotype is a possible non-modifiable risk factor for cognitive impairment, which we could not include in our study due to constraints in data availability." (PMID 39363845, 2024). "Most importantly, plasma APOE, MMP9, S100A8, UBR5 PLA2G7, and STAT5B play a potentially crucial role in the progression of cognitive disorders." (PMID 38883967, 2024). "Additionally, the APOE gene that is suggested to be involved in amyloid-beta metabolism, neuroinflammation, tau- induced neurodegeneration, and blood–brain barrier disruption, could affect the age of onset of cognitive impairment." (PMID 37779209, 2023). "However, other factors could trigger cognitive impairment and do not necessarily involve specific APOE polymorphisms, such as inflammation, cerebral ischemia, and hypoxemia." (PMID 36046159, 2022). "In an APP/APOE knockout mouse, inhibition of the TGFB/SMAD2 pathway activity in astrocytes has been shown to increase amyloid plaque formation and cognitive impairment." (PMID 35573689, 2022). "It has been hypothesized that vulnerability to cognitive deficits is increased in carriers of the APOE-e4 allele due to a limited response to physiological challenges, and that OSA may potentiate neuroinflammatory processes associated with APOE-e4 by augmenting inflammation through hypoxia." (PMID 36688173, 2022). "We identified 73 healthy control (HC) with APOE ε3/ε3, 61 mild cognitive impairment (MCI) subjects with APOE ε3/ε3, 24 HC with APOE ε2/ε3, and 10 MCI subjects with APOE ε2/ε3 from the ADNI database." (PMID 33994988, 2021). "APOE ε4 non-carriers with AD showed lower expression of proteins involved in synapse structure and function when cognition was normal and lower concentrations of proteins that were associated with complement and other inflammatory processes when cognitive impairment was mild." (PMID 32460813, 2020). "AD and mild cognitive impaired individuals have 30% less ABCA1-mediated cholesterol efflux capacity toward CSF than healthy individuals; this effect was APOE genotype-independent." (PMID 32882843, 2020).
Cognitive impairment (continued). "More longitudinal high-powered studies investigating the interplay between the APOE genotype, MDD and cognitive deficits, as well as neuronal processes involved are needed." (PMID 31191441, 2019). "As expected, MCI-AD patients presented with a more severe cognitive impairment at baseline (significantly lower MMSE and MoCA and higher ADAS-Cog scores) than MCI-St patients, and were also more frequently APOE-ε4 carriers." (PMID 29558986, 2018). "Thus, they may offer targets for the remediation of APOE-specific cognitive impairments." (PMID 28291794, 2017). "On the other hand, the effect on the APOE*E4 cognitive tests is controversial in young people and in certain studies it has been found that the carriers of this allele, which is the main genetic risk factor for cognitive impairment, even perform better than the non-carriers." (PMID 27861563, 2016). "Our present study investigated the possible mechanisms of cognitive impairment of ApoE-KO mouse fed with western type diet and the protective effects of 7,8-DHF in improving spatial learning and memory in ApoE-KO mouse." (PMID 27965573, 2016). "In the APOE E4 noncarriers, odds ratio (OR) of the UACR values ≥300 mg/g (macroalbuminuria) for cognitive impairment was 1.87 (95% CI, 1.29–2.72) compared to UACR values of <15 mg/g, while in the APOE E4 carriers, OR was 3.56 (1.34–9.42)." (PMID 25530658, 2014). "The development of neurodegeneration and cognitive deficits was corrected by injections of COG112 or COG133, novel mimetics of apolipoprotein-E (apoE) with neuroprotective activities." (PMID 19997607, 2009). "Although outcome studies have implicated APOE ε4 as a risk allele for cognitive impairment following subacute phase of aneurysmal SAH and a recent meta-analysis showed marginal association of ε4 carriers with SAH, the biological role of APOE in the etiology of SAH remains unclear." (PMID 17672902, 2007). "Thus, this indicates that PD-related cognitive impairment and DLB cannot be fully explained by APOE status alone." (PMID 40052092, 2025). "Further, the link between objective cognitive impairment, depression and APOE-ε4 does not appear to be specific to Post-COVID symptoms." (PMID 40021517, 2025). "Our observations are consistent in suggesting APOE ε4 is linked to agitation and other NPS by mechanisms that are not directly derived from cognitive impairment." (PMID 39974048, 2025). "This study examines the effects of Apolipoprotein E (APOE) genotypes and healthy lifestyles on life expectancy with and without cognitive impairment (CI) in Chinese older adults." (PMID 40226865, 2025). "In conclusion, among people with and without cognitive impairment, the prevalence of tau pathology as determined by PET imaging was associated with Aβ status, age, sex and APOE genotype." (PMID 40670684, 2025). "Furthermore, subsequent research on the role of plasma ceramide levels in PD patients with cognitive deficits should account for the influence of the GBA and APOE genotypes." (PMID 39428566, 2024). "Subjects without cognitive impairment had average atrophy rates of 6 mL/year for the whole brain and 0.06 mL/year for the hippocampus, for APOE-negative individuals (APOE-positive individuals not reported)." (PMID 39210976, 2024). "Furthermore, in individuals with mild cognitive impairment (MCI) or AD, hippocampal volume decreases have been observed in relation to APOE ε4 status." (PMID 38762725, 2024). "Therefore, a well-established model integrating aging, ApoE ε4 genotype and elevated platelet GSK-3β activities has great potential to predict the development of cognitive impairment in patients with T2DM." (PMID 38660514, 2024). "Neuropsychological assessment in patients with HS-TLE and patients with HS-TLE showed a similar proportion of APOE ε4 carriers and non-carriers presenting severe and non-severe cognitive impairments." (PMID 39337715, 2024).
Cognitive impairment (continued). "Neuropsychological tests were grouped into nine domains, patients were categorized according to their APOE ε4 carrier status, and their cognitive impairment outcome was classified into severe or non-severe impairments." (PMID 39337715, 2024). "On the other hand, other studies reported no significant sex difference in the risk of developing mild cognitive impairment (MCI) and/or AD in older participants (aged between 55 and 85 years) that were carrying the APOE ε3/ε4 genotype." (PMID 36908785, 2023). "For mild cognitive impairment due to AD or a mild AD trial, the performance of enrichment based on AD Course Map was not significantly different from targeting APOE-ε4 carriers." (PMID 36765056, 2023). "In the current study, we aimed to assess the plasma apoE levels (total and isoform levels) in a cohort of older B/AA and NHW participants with normal cognition, mild cognitive impairment (MCI), or mild AD dementia with detailed neuropsychological, CSF, and magnetic resonance imaging (MRI) analysis." (PMID 37400888, 2023). "Though the differences were not significant, there is an observed 4.3-year discrepancy for age at onset of cognitive impairment when comparing APOE Ɛ4 carriers who drink heavily to non-drinkers who do not carry the allele." (PMID 35275952, 2022). "Nevertheless, the interaction term between baseline annual average NDVI and APOE ε4 status on cognitive impairment was not significant." (PMID 36141977, 2022). "ApoE2, but not ApoE3 or ApoE‐KO, mice showed reduced sevoflurane‐induced pTau elevation and cognitive impairment." (PMID 35810473, 2022). "First, we examined the feasibility of the screening and recruitment protocol, which was designed to recruit five older adults with possible mild cognitive impairment (MCI) and an apolipoprotein E (APOE) €4 allele, and five with only MCI and no genetic risk." (PMID 35065656, 2022). "The role of APOE ε2ε4 in developing AD dementia or mild cognitive impairment (MCI) was examined in non-Latino white patients to control for the influence of ethnic group." (PMID 35197840, 2022). "The total study sample comprised 1,076 APOE ε4 carriers (17.5%) and 5,084 APOE ε4 noncarriers (82.5%) with an average age of 90.1 ± 7.2 years, and among them, 1,267 (24.9%) had cognitive impairment." (PMID 34061824, 2021). "In the multivariable logistic regression, the APOE ε4 noncarriers had 17% lower odds of cognitive impairment (95% CI: 1% to 31%, P = 0.042) compared with those carrying the ε4 allele." (PMID 34061824, 2021). "APOE genotype has long been known to affect the response to n-3 PUFA interventions in healthy participants and in patients with cardiovascular and cognitive disorders." (PMID 34604280, 2021). "In the subgroup analyses by APOE genotype, among APOE ε4 noncarriers, the odds of cognitive impairment in participants with a healthy lifestyle was lower than that in those with an unhealthy lifestyle (OR: 0.47, 95% CI: 0.37 to 0.60, P < 0.001)." (PMID 34061824, 2021). "The current prevalence of cognitive impairment was not significantly different between APOE ε4 carriers and non-carriers." (PMID 32231559, 2020). "Recently, graph theory analysis of brain connectivity from EEG signals combined with apolipoprotein E genotyping has been proposed to distinguish prodromal to AD from non-prodromal mild cognitive impairment (MCI) subjects." (PMID 32719795, 2020). "This allowed us to focus on frailty in the absence of cognitive impairment and to account for APOE e4 status." (PMID 33195297, 2020). "Difference of the cognitive impairment, serum lipid levels, and other covariates between APOE ε4 carriers and non-carriers." (PMID 32231559, 2020). "Improving the lipidated state of apoE ameliorates cognitive deficits in the presence or absence of amyloid pathology regardless of APOE genotype." (PMID 32882843, 2020).
Cognitive impairment (continued). "The stratified analyses according to APOE ε4 status showed that the current prevalence of cognitive impairment was still not significantly different between any of the serum lipid groups in APOE ε4 carriers or non-carriers." (PMID 32231559, 2020). "The association between higher levels of residential greenness and lower risks of cognitive impairment was significant only among the APOE non-ε4 carriers but not the ε4 carriers." (PMID 31919381, 2020). "Compared to APOE ε4 non-carriers, the APOE ε4 carriers had a 15% higher odds of cognitive impairment (OR: 1.15, 95% CI: 1.05, 1.26)." (PMID 31919381, 2020). "Following our selection criteria, we ended up with 24 ApoE ε4 carriers and 24 ApoE ε4 non-carriers with mild cognitive impairment (MCI) ranging from 55 to 85 years of age." (PMID 30991617, 2019). "Compared with those who had no cognitive impairment at baseline, participants with MCI were older, more likely to be men, less educated, and had APOE ε4 alleles and prevalent heart failure." (PMID 31074810, 2019). "Although apoE interacts with amyloid, it should be noted that plaque load does not correlate well with cognitive impairments, highlighted most obviously by people with substantial plaque burdens and normal cognition." (PMID 31186040, 2019). "We found that the nucleus basalis of Meynert mean diffusivity mean voxel value remained a predictor of cognitive impairment when adjusted for the UPSIT, RBDSQ, Geriatric Depression Scale, MDS-UPDRS-III, APOE, amyloid-β:tau ratio, axial gait, and white matter lesion volume." (PMID 29701787, 2018). "ApoE has been found to regulate clearance of Aβ in an isoform-dependent fashion (E2>E3>E4) in animal models of AD and in humans without cognitive impairment." (PMID 30618606, 2018). "Thus, this ApoE-KO mouse model faithfully replicates the stenosis of common carotid artery (CCA) and cognitive impairment following atherosclerotic deposition and global cerebral hypoperfusion." (PMID 30337867, 2018). "We found that nucleus basalis of Meynert grey matter mean voxel value remained a predictor of cognitive impairment when adjusted for UPSIT, RBDSQ, Geriatric Depression Scale, MDS-UPDRS-III, APOE, amyloid-β:tau, axial gait score, and white matter lesions volume." (PMID 29701787, 2018). "Previous studies in the Newcastle cohort failed to establish a relationship between APOE ε4 with post-stroke cognitive impairment at 3 months after the stroke but predicted decline at 1-year follow up." (PMID 29311794, 2017). "Cognitive impairment, according to SPMSQ evaluation, was not significantly related to P2X7R genotypes, whilst it trended to be positively linked to the presence of APOE-ε4 genotype (p=0.07)." (PMID 28840058, 2017). "DP1 was associated with a 74% increased risk of cognitive impairment (P = 0.03) compared with DP2 after adjustment for all covariates (Model 4), but it was attenuated by apoE ε4 genotype (1.63; CI: 0.95, 2.79; P = 0.07) (data not shown)." (PMID 26740685, 2016). "The aim of this investigation was to assess the effect of galantamine, an acetylcholinesterase inhibitor and allosteric modulator of nicotinic receptors, on brain atrophy in individuals with mild cognitive impairment (MCI), and to assess effect modification by apolipoprotein E (APOE) genotype." (PMID 25478019, 2014). "Taken together therefore, the lack of functional ApoE present in AD is likely to directly contribute to the cognitive impairment seen in this disease." (PMID 24971061, 2014). "We sought to define how the early cognitive deficits in newly diagnosed patients with Parkinson’s disease map onto changes in brain activation, and how these activations in patients varied as a function of the common genetic variations in COMT, MAPT and APOE." (PMID 25080285, 2014). "Thirdly, we did not adjust for other potential confounding factors, such as APOE genotype, socio-economic status and family history of cognitive impairment." (PMID 20932304, 2010).